KIF13A (kinesin family member 13A)
Description:
Plus end-directed microtubule-dependent motor protein involved in intracellular transport and regulating various processes such as mannose-6-phosphate receptor (M6PR) transport to the plasma membrane, endosomal sorting during melanosome biogenesis and cytokinesis. Mediates the transport of M6PR-containing vesicles from trans-Golgi network to the plasma membrane via direct interaction with the AP-1 complex. During melanosome maturation, required for delivering melanogenic enzymes from recycling endosomes to nascent melanosomes by creating peripheral recycling endosomal subdomains in melanocytes. Also required for the abscission step in cytokinesis: mediates translocation of ZFYVE26, and possibly TTC19, to the midbody during cytokinesis.
Synonyms: RBKIN; bA500C11.2
Tractability: Antibody: UniProt places it where antibodies can reach, with medium confidence. PROTAC: ubiquitination databases record sites on it; its protein half-life has been measured.
Gene: Protein-coding gene on chromosome 6 (17,759,183 to 17,987,635, reverse strand). Ensembl gene ENSG00000137177.
Subcellular location: Cytoplasm, cytoskeleton, microtubule organizing center, centrosome; Midbody; Endosome membrane; Golgi apparatus membrane
Subcellular location (Human Protein Atlas): Mid piece; Principal piece
Pathways (Reactome):
Metabolism of proteins: Association of TriC/CCT with target proteins during biosynthesis
Gene Ontology:
Molecular function: protein binding; microtubule motor activity; ATP binding; microtubule binding
Biological process: endosome to lysosome transport; intracellular protein transport; melanosome organization; regulation of cytokinesis; vesicle cargo loading; Golgi to plasma membrane protein transport; plus-end-directed vesicle transport along microtubule; establishment of protein localization; microtubule-based movement
Cellular component: centrosome; endosome membrane; midbody; kinesin complex; trans-Golgi network membrane; cytoplasm; Golgi membrane
Genetic constraint (gnomAD): Loss-of-function variants: 55 observed, 146.23 expected, observed/expected ratio (o/e) 0.38, 90% interval 0.3 to 0.47. The upper end of that interval is the gene's LOEUF score, 0.47, which puts it in group 2 of 6, group 1 being the genes least tolerant of losing a copy. Missense variants: 1,640 observed, 1,911.6 expected, observed/expected ratio (o/e) 0.86, 90% interval 0.82 to 0.89. Synonymous variants: 685 observed, 712.84 expected, observed/expected ratio (o/e) 0.96, 90% interval 0.9 to 1.02.
Homologues: Orthologues: chimpanzee KIF13A (99% identical), macaque KIF13A (97% identical), rabbit KIF13A (95% identical), dog KIF13A (93% identical), pig KIF13A (92% identical), rat Kif13a (92% identical), mouse Kif13a (90% identical), guinea pig KIF13A (89% identical), tropical clawed frog kif13a (77% identical), zebrafish kif13a (65% identical). Paralogues in human: KIF13B (55% identical), KIF1A (28% identical), KIF1B (27% identical), KIF1C (21% identical), KIF16B (20% identical), KIF14 (19% identical), KIF21B (15% identical), KIF21A (14% identical), CENPE (14% identical), KIF17 (14% identical), KIF4B (14% identical), KIF4A (13% identical), and 29 more.
Diseases named in the same sentence as KIF13A in open-access papers:
KIF13A is named in the same sentence as 20 diseases in open-access papers, as found by Europe PMC text mining. Sharing a sentence is not in itself a finding about the gene and the disease. The quoted sentences say what the papers report.
Anxiety (4 papers, 2019 to 2025). Intense feelings of nervousness, tension, or panic often arise in response to interpersonal stresses. "Furthermore, KIF13A transports the 5HT1A receptor (5HT1AR), a serotonin receptor family protein, in hippocampal neurons, and disrupting this transport leads to anxiety-related behavioral phenotypes." (PMID 39885501, 2025). "In neuronal cells, the absence of KIF13A causes reduced cell surface expression of a set of serotonin receptors, leading to elevated anxiety phenotype in KIF13A knockout mice." (PMID 35547822, 2022). "A recent study on mice lacking KIF13A reported elevated anxiety-related traits through a reduction in the serotonin 5HT(1A)R receptor transport and reduced expression of the receptor in neuroblastoma cells and hippocampal neurons." (PMID 32111185, 2020).
breast carcinoma (3 papers, 2011 to 2024). "We analysed the effects of different splicing events using the OncoSplicing public database, revealing that the percentage spliced in (PSI) values for KIF13A exon 26 and MAP2K7 exon 2 were higher in normal breast tissue than in breast cancer tissue." (PMID 38725048, 2024). "Interestingly, we also observed that the average expression of KIF13A and TTC19 was significantly lower in high vs. low grade breast cancers." (PMID 21455500, 2011). "The downregulation of FYVE-CENT, BECN 1, KIF13A and TTC19 in advanced breast cancer is consistent with the possibility that these proteins may participate in tumor suppression." (PMID 21455500, 2011).
lung carcinoma (3 papers, 2023 to 2025). "The case diversifies the array of ALK fusion partners and holds clinical relevance in refining therapeutic choices for KIF13A-ALK fusion-associated lung cancer." (PMID 38155713, 2023). "Subsequent work should further elucidate the biological characteristics and optimal treatment interventions for lung cancers bearing the KIF13A-ALK fusion gene." (PMID 38155713, 2023). "Members of the kinesin-3 family, KIF13A and KIF13B, are also involved in genetic rearrangements, with KIF13A-RET, KIF13A-ALK, and KIF13B-NRG1 being identified in LUAD or not otherwise specified lung cancer patients." (PMID 40002279, 2025).
lung adenocarcinoma (2 papers, 2022 to 2023). A carcinoma that arises from the lung and is characterized by the presence of malignant glandular epithelial cells. "A KIF13A fusion with RET sequences encoding tyrosine kinase (KIF13-RET) has been reported in lung adenocarcinoma." (PMID 35547822, 2022). "This is the first reported case of a 74-year-old female with stage IV lung adenocarcinoma, featuring a novel Kinesin Family Member 13A (KIF13A)-ALK fusion, identified via next-generation sequencing (NGS) and confirmed with fluorescence in situ hybridization (FISH)." (PMID 38155713, 2023). "Within the scope of this study, we present a noteworthy discovery: the identification of an unreported fusion involving KIF13A and ALK in a patient with lung adenocarcinoma." (PMID 38155713, 2023).
schizophrenia (2 papers, 2009 to 2025). A major psychotic disorder characterized by abnormalities in the perception or expression of reality. "Up-regulation of KIF3 was found in patient samples, and KIF2 and KIF13A were also considered genetic susceptibility genes for schizophrenia." (PMID 40964093, 2025).
acute lymphoblastic leukaemia (1 paper, 2022). "Moreover, Rho-ROCK promotes metastasis of acute lymphoblastic leukaemia (ALL) cells in response to CCL25, while KIF13A regulates RhoB vesicular recycling promotes bleb-based amoeboid migration in ALL." (PMID 36699013, 2022).
bladder urothelial cancer (1 paper, 2022). "Kif13a gene was also amplified in more than 6% and 4% of patients diagnosed with bladder urothelial cancer and diffuse large-B cell lymphoma (DLBC), respectively." (PMID 35122963, 2022).
celiac disease (1 paper, 2015). An autoimmune genetic disorder with an unknown pattern of inheritance that primarily affects the digestive tract. "Seven genes were down-regulated in the biopsies of celiac disease patients, among them NTS down-regulated 3.6 fold and the INSR, APPL2, ADCY9, GLS, HSPB1 and KIF13A 1.5-2.2 fold in the patient group (p < 0.001)." (PMID 26123480, 2015).
liver cancer (1 paper, 2022). An epithelial or non-epithelial malignant neoplasm that arises from the liver. "Liver cancer patients with a high expression of KIF13A had a significantly lower survival probability than those with a low expression." (PMID 35122963, 2022). "We performed a Kaplan-Meier survival analysis of liver cancer patients with low or high mRNA expression of the Kif13a gene through the Pathology Atlas." (PMID 35122963, 2022).
ovarian serous cystadenocarcinoma (1 paper, 2022). A malignant serous cystic epithelial neoplasm arising from the ovary. "More than seven in 100 women diagnosed with ovarian serous cystadenocarcinoma presented a Kif13a gene amplification." (PMID 35122963, 2022).
tumor (8 papers, 2011 to 2026). "Focusing on the top six mutant genes in high-risk samples, an in vitro assay demonstrated that EPHB1 and KIF13A were significantly overexpressed in tumor cells and that low levels of EPHB1 were associated with a better prognosis." (PMID 40548257, 2025). "In somatic mutation analysis, EPHB1 and KIF13A from the top six mutant genes were overexpressed in 22RV1 and PC-3 tumor cells, and low levels of EPHB1 indicated a better prognosis." (PMID 40548257, 2025). "We observed a trend of upregulation of multiple genes (especially EPHB1 and KIF13A) in two PRAD cell lines (22RV1 and PC-3) (p < 0.05), and EPHB1, with the highest mutation frequency, was also significantly upregulated in C4-2, DU145, and C4-2B tumor cells (p < 0.05)." (PMID 40548257, 2025). "A rare KIF13A-RET fusion involving exon 19 of KIF13A and exon 12 of RET was detected in tumor tissue." (PMID 39057153, 2024). "Immunocytochemistry showed KIF13A and KIF26A mainly localized in cytoplasm and membrane, and KIF13B and KIF4A mainly concentrated at membrane and nuclear that significantly upregulated in tumor samples." (PMID 36837615, 2023). "Finally, KIF4A, KIF13A, KIF13B, and KIF26A were identified from the HPA database, and all these KIFs differentially expressed between normal and tumor samples." (PMID 36837615, 2023). "Epigenome-wide association analysis identified clusters of CpGs on chromosomes 6 and 7, mapping to genes such as KIF13A and GET4, reinforcing the concept that methylation changes in cytoskeleton- and transport-related genes could contribute to tumor progression." (PMID 41597272, 2026).
cancer (5 papers, 2021 to 2023). A tumor composed of atypical neoplastic, often pleomorphic cells that invade other tissues. "Among others, E2f1, E2f3, Kif13a, Rxra, Rxrb, and Rxrg were the most common and prominent genes that emerged in our analysis associated with multiple cancer-related pathways." (PMID 37047531, 2023). "Dysfunction of KIF13A has been implicated in many cancers, and its enhanced amplification is observed in some cancers." (PMID 35547822, 2022). "We next investigated if the expression level of KIF3A, KIF13A, and KIF9 correlates with cancer progression." (PMID 35122963, 2022). "Our data suggest that KIF13A is a crucial player of MT1-MMP intracellular trafficking pathways and mediate MT1-MMP-dependent invasion of cancer cells." (PMID 35122963, 2022). "The analysis of the TCGA database revealed that the expression profile of KIF13A and KIF9 is altered in several cancer types." (PMID 35122963, 2022). "Depletion of KIF13A or AP1S2 mitigates ZEB1-dependent focal adhesion dynamics, front-rear axis polarization, and cancer cell motility." (PMID 34732702, 2021).
infection (3 papers, 2017 to 2025). The state of being infected such as from the introduction of a foreign agent such as serum, vaccine, antigenic substance or organism. "Similarly, KIF13A transports Rab11A-positive vesicles containing ribonucleoproteins of influenza A virus to the cell surface during infection." (PMID 35547822, 2022). "We next examined the possibility of drug-mediated regulation of KIF13A and KIF13A-motorized M6PR during infection." (PMID 28496990, 2017). "Indeed, we found a significant downregulation of KIF13A, β1-adaptin and cell-surface M6PR in OVA-specific CD8+ T cells on day 7 of infection, when Gzm-B level remains very high, as well as a significantly reduced T-cell contraction (day 15)." (PMID 28496990, 2017).
psychiatric disorder (2 papers, 2016 to 2025). A disorder characterized by behavioral and/or psychological abnormalities, often accompanied by physical symptoms. "As a candidate for a crucial Kifs gene that is likely related to microglia polarization, we selected psychiatric disorder-related KIFs (KIF3A, KIF17, KIF1A, KIF1B, and KIF13A)." (PMID 39885501, 2025).
neurodegenerative disease (1 paper, 2025). A disorder of the central nervous system characterized by gradual and progressive loss of neural tissue and neurologic function. "Correspondingly, kinesin family member 13A (KIF13A, 6p22.3) is a component of axonal transport implicated in developmental and neurodegenerative diseases." (PMID 40631452, 2025).
KIF13A also shares sentences with these, for which no sentence is quoted: diffuse large B-cell lymphoma (1 paper); gastric cancer (1); glioma (1); neuroblastoma (1); triple-negative breast carcinoma (1).